FCN1 (ficolin 1)
Description:
Extracellular lectin, which acts as a pattern recognition receptor that initiates the lectin pathway of the complement system, a cascade of proteins that leads to phagocytosis and breakdown of pathogens and signaling that strengthens the adaptive immune system. Specifically recognizes and binds carbohydrates on the pathogen surface, activating the MASP1 serine protease and initiating the proteolytic cascade of the lectin complement pathway. Binds preferentially to 9-O-acetylated 2-6-linked sialic acid derivatives and to various glycans containing sialic acid engaged in a 2-3 linkage. May also activate monocytes through a G protein-coupled receptor, FFAR2, inducing the secretion of interleukin-8/IL-8.
Synonyms: FCNM
Tractability: Small molecule: a structure with a bound ligand is known; it has a high-quality binding pocket. Antibody: UniProt places it where antibodies can reach, with high confidence; its Gene Ontology location is reachable by antibodies, with high confidence; UniProt predicts a signal peptide or a membrane-spanning region. PROTAC: its protein half-life has been measured.
Gene: Protein-coding gene on chromosome 9 (134,903,232 to 134,917,954, reverse strand). Ensembl gene ENSG00000085265.
Subcellular location: Secreted; Cell surface
Pathways (Reactome):
Immune System: Ficolins bind to repetitive carbohydrate structures on the target cell surface; Initial triggering of complement; Lectin pathway of complement activation; Neutrophil degranulation
Gene Ontology:
Molecular function: G protein-coupled receptor binding; pattern recognition receptor activity; protein binding; sialic acid binding; antigen binding; carbohydrate derivative binding; signaling receptor binding
Biological process: cell surface pattern recognition receptor signaling pathway; complement activation, lectin pathway; G protein-coupled receptor signaling pathway; host-mediated suppression of symbiont invasion; positive regulation of interleukin-8 production; positive regulation of opsonization; protein localization to cell surface; proteolysis; recognition of apoptotic cell
Cellular component: cell surface; extracellular matrix; extracellular region; plasma membrane; serine-type endopeptidase complex; symbiont cell surface; external side of plasma membrane; ficolin-1-rich granule lumen; secretory granule lumen
Genetic constraint (gnomAD): Loss-of-function variants: 41 observed, 35.8 expected, observed/expected ratio (o/e) 1.15, 90% interval 0.89 to 1.49. The upper end of that interval is the gene's LOEUF score, 1.49, which puts it in group 6 of 6, group 1 being the genes least tolerant of losing a copy. Missense variants: 402 observed, 410.62 expected, observed/expected ratio (o/e) 0.98, 90% interval 0.9 to 1.06. Synonymous variants: 156 observed, 159.13 expected, observed/expected ratio (o/e) 0.98, 90% interval 0.86 to 1.12.
Homologues: Orthologues: macaque FCN1 (92% identical), guinea pig FCN1 (79% identical), rat Fcnb (75% identical), dog FCN2 (73% identical), mouse Fcnb (72% identical), chimpanzee FCN1 (57% identical). Paralogues in human: FCN2 (76% identical), FCN3 (44% identical), TNC (44% identical), TNR (43% identical), TNXB (43% identical), TNN (40% identical), FIBCD1 (34% identical), FGB (32% identical), MFAP4 (32% identical), ANGPTL2 (32% identical), FGL2 (31% identical), ANGPT1 (31% identical), and 13 more.
Diseases named in the same sentence as FCN1 in open-access papers:
FCN1 is named in the same sentence as 103 diseases in open-access papers, as found by Europe PMC text mining. Sharing a sentence is not in itself a finding about the gene and the disease. The quoted sentences say what the papers report.
COVID-19 (22 papers, 2020 to 2025). A disease caused by infection with severe acute respiratory syndrome coronavirus 2. "Independent differential gene expression analysis identified striking similarities in the pathogenic pathways of COVID-19 pneumonitis FCN1+ and active RA synovitis CD48hiS100A12+ clusters." (PMID 34143756, 2021). "The iMO gene expression profile is also similar to those of human FCN1-monocytes recovered from the broncho-alveolar lavage of COVID-19 patients with acute respiratory disease syndrome." (PMID 40920821, 2025). "Single-cell transcriptomic analysis of BAL macrophages in patients with COVID-19-related ARDS reveals that a ficolin-1+/osteopontin+ subpopulation of macrophages appear to play a pathogenic role." (PMID 37180160, 2023). "Enrichment of FCN1-expressing macrophages is observed in BALF of COVID-19 patients with severe/critical disease relative to patients with moderate infection and controls." (PMID 34239884, 2021). "The BALF FCN1+ and FCN1+SPP1+ macrophage clusters from severe COVID-19 patients shared transcriptomic profiles with STM CD48hiS100A12+ and CD48+SPP1+ clusters from active RA, respectively." (PMID 34143756, 2021). "The alveolar tissue of COVID-19 patients abundantly presents two distinct macrophage clusters expressing ficolin-1 (FCN1), which can be differentiated by their relative expression of secreted phosphoprotein 1/osteopontin (SPP1)." (PMID 34943795, 2021). "We observed the CXCL10+ CCL2+ and FCN1+ states are abundant in severe COVID-19 compared to healthy BALF." (PMID 33879239, 2021). "Among these, we found two inflammatory CXCL10+ CCL2+ and FCN1+ macrophage states that are shared between COVID-19 and several of the inflammatory diseases we analyzed." (PMID 33879239, 2021). "In severe COVID-19, we observed a shift in cell frequency between the FCN1+ and CXCL10+ CCL2+ macrophages (Wilcoxon rank-sum test P = 1.4e−07)." (PMID 33879239, 2021). "COVID-19 BALF FCN1+ and FCN1+SPP1+ macrophage clusters are transcriptionally similar to CD48hiS100A12+ and CD48+SPP1+ clusters that drive RA synovitis." (PMID 34143756, 2021). "The CXCL10+ CCL2+ inflammatory macrophages displayed significantly higher expression of CXCL10, CXCL11, CCL2, CCL3, GBP1, and IDO1 in severe COVID-19, inflamed RA, and CD compared to the FCN1+ macrophages." (PMID 33879239, 2021). "FABP4 was preferentially expressed in healthy controls and in patients with moderate COVID-19, while FCN1 and SPP1 were expressed in patients with severe COVID-19." (PMID 32612615, 2020). "Ficolin-1 is a known activator of the complement system and innate immunity through recognition of pathogen-associated molecular patterns (PAMPs), while VEGFR2 has been related to COVID-19 progression." (PMID 36710882, 2022). "We found that bronchoalveolar lavage fluid (BALF) macrophage clusters FCN1+ and FCN1+SPP1+ predominant in severe COVID-19 were transcriptionally related to synovial tissue macrophage (STM) clusters CD48hiS100A12+ and CD48+SPP1+ that drive rheumatoid arthritis (RA) synovitis." (PMID 34143756, 2021). "Monocyte-derived macrophages from BALF of COVID-19 patients showed increased ficolin-1 mRNA expression, which may support local activation of the MBL pathway." (PMID 34054832, 2021). "The hierarchical analysis and comparison of cluster markers also indicate a shared transcriptional profile of COVID-19 FCN1+SPP1+ and synovitis CD48+SPP1+ clusters consisting of 86 common marker genes including SPP1, which have broad proinflammatory and fibrotic functions." (PMID 34143756, 2021). "In this study, we built a single-cell immune reference from multiple inflamed disease tissues and identified two inflammatory macrophage states, CXCL10+ CCL2+ and FCN1+ inflammatory macrophages, that were shared between COVID-19 and inflammatory diseases such as RA, CD, and UC." (PMID 33879239, 2021).
COVID-19 (continued). "Indeed, an increased population of FCN1+ macrophages was found in the BAL fluid from critically ill COVID-19 cases when compared to that from mild cases, thus implicating its role in resulting overt inflammatory sequence of events followed by poor prognosis." (PMID 32595947, 2020). "Besides the insight provided by autopsy studies regarding the immune landscape of the pulmonary system in the context of COVID-19, work by Liaoet al.60 demonstrated the role of FCN1+ macrophages in aggravating the severity of pulmonary pathology upon infection by SARS-CoV-2." (PMID 32595947, 2020). "Macrophages: Macrophages involved in COVID-19, are primarily inflammatory monocyte-derived, which express FABP4, ficolin-1 (FCN1), and SPP1 in case of mild and severe disease respectively." (PMID 35002519, 2022). "Macrophages with FABP4, known as the alveolar macrophages, were reduced while macrophages with FCN1 and SPP1, considered as the monocyte-derived proinflammatory macrophages, were strikingly increased in COVID-19 patients." (PMID 33762651, 2021). "Macrophage subset classification markers, including FCN1, SPP1, and FABP4, were differentially expressed by circulating and BALF monocyte-macrophages from patients with mild or severe COVID-19." (PMID 33101705, 2020). "A single-cell study of bronchoalveolar lavage fluid (BALF) in intubated COVID-19 patients identified two inflammatory macrophage subsets—one characterized by CCL2, CCL3, and CXCL10 expression and a second by FCN1 and S100A8—as potential mediators of pathology in this late-stage disease." (PMID 33879239, 2021). "Moreover, highly proinflammatory monocyte-derived FCN1+ macrophages were present in bronchoalveolar lavage fluid of the severe COVID-19 patients but not the mild patients." (PMID 32519302, 2020).
autoimmune disease (9 papers, 2017 to 2025). A disorder resulting from loss of function or tissue destruction of an organ or multiple organs, arising from humoral or cellular immune responses of the individual to their own tissue constituents. "Given its significance in disease pathogenesis, FCN1 gene polymorphisms have been associated with autoimmune disorders such as systemic lupus erythematosus and rheumatoid arthritis, highlighting its involvement in autoimmunity." (PMID 39139822, 2024). "Most previous studies have only focused on the aberrant expression of FCN1 in some autoimmune diseases and its correlation with disease activity." (PMID 36932401, 2023). "Serum levels of FCN1 are elevated in vasculitis syndrome and arthritis, and FCN1 has thus gained attention as a potential therapeutic target in autoimmune diseases." (PMID 37146011, 2023). "Ficolin-1 levels in plasma have previously been positively associated with white blood cell (WBC) counts in individuals with autoimmune diseases and children with cancer, but not in healthy individuals." (PMID 40422078, 2025). "Considering the pivotal role of inflammation in the tumor microenvironment, understanding FCN1’s function in autoimmune diseases, infection, and inflammation is well-established, but its involvement in cancer remains unclear." (PMID 39139822, 2024). "Recent reports have described the involvement of FCN1 in autoimmune diseases such as rheumatoid arthritis and FCN1 level might reflect the degree of inflammation." (PMID 36483554, 2022). "In addition, FCN1 inhibition alleviated the symptoms of multiple autoimmune diseases in mouse models, including collagen-induced RA mice, further suggesting its crucial role in the development of inflammation." (PMID 35627163, 2022). "Ficolin 1 is considered as a target for autoimmune diseases therapy." (PMID 33375205, 2020). "Moreover, Wb of serum obtained before and after IVIG therapy from patients with other autoimmune and systemic inflammatory diseases to which IVIG therapy has been successfully applied could provide support for the generally applicability of our FCN1 findings to other autoimmune diseases." (PMID 28900133, 2017).
rheumatoid arthritis (9 papers, 2018 to 2025). A chronic, systemic autoimmune disorder characterized by inflammation in the synovial membranes and articular surfaces. "Polymorphisms in the FCN1 gene coding for M-ficolin have been described to be associated with the susceptibility to develop rheumatoid arthritis." (PMID 31500626, 2019). "FCN1 polymorphisms were associated with increased fatal outcome in patients with systemic inflammation, susceptibility to rheumatoid arthritis and leprosy." (PMID 30619357, 2018). "Polymorphisms in the ficolin 1 gene (FCN1) are associated with susceptibility to the development of rheumatoid arthritis (RA)." (PMID 35967305, 2022). "A systematic literature review was performed using the following keywords “gene (FCN1/FCN2/FCN3)”, “Polymorphism/Genetic Variant”, and “rheumatoid arthritis” in different databases until January 2022." (PMID 36569030, 2022). "The present systematic review was conducted to synthesize the results of the studies in order to establish the impact of polymorphisms in the ficolin-coding genes FCN1, FCN2, and FCN3 on the susceptibility to develop rheumatoid arthritis." (PMID 36569030, 2022). "On the other hand, high levels of ficolin-1 in patients with rheumatoid arthritis have been reported, and anti-ficolin-1 Ab ameliorated symptom of a mouse model of collagen antibody-induced arthritis." (PMID 32915797, 2020). "The FCN1 gene variants, particularly rs2989727 and rs1071583, have been reported to be linked to increased risk of developing rheumatoid arthritis in Brazilian and Belgian populations, whereas no such associations were observed for FCN2 or FCN3 variants." (PMID 41285030, 2025). "The FCN1 gene variants rs2989727 and rs1071583 are associated with the risk of developing rheumatoid arthritis in populations from Brazil and Belgium, but not in FCN2 and FCN3 gene variants." (PMID 36569030, 2022). "In addition, serum ficolin-1 was positively correlated with disease activity in patients with rheumatoid arthritis (RA) and juvenile idiopathic arthritis." (PMID 32915797, 2020). "Both polymorphisms in the FCN1 gene (rs2989727 and rs1071583), but not in FCN2 and FCN3, are associated with the risk of developing rheumatoid arthritis in populations from Brazil and Belgium." (PMID 36569030, 2022).
Arthritis (6 papers, 2018 to 2025). Inflammation of a joint. "Furthermore, both ficolin B deficiency and the administration of anti-ficolin-1 mAb were found to decrease the severity of collagen Ab–induced arthritis, with a reduction in the infiltration of synovial macrophages and neutrophils." (PMID 37996869, 2023). "Reference mapping showed that the majority of ICI-arthritis myeloid cells mapped onto four RA myeloid clusters: IL1B + FCN1 + HBEGF+, STAT1+ CXCL10+, SPP1+, and MERTK+ HBEGF+ clusters." (PMID 40662950, 2025). "It was previously reported that anti-FCN1 monoclonal antibody could alleviate experimental arthritis in the mouse model." (PMID 36932401, 2023). "Blockade of FCN1 reduces inflammation in a murine model of arthritis, suggesting that downregulation of FCN1 may be a mechanism of therapeutic intravenous immunoglobulin." (PMID 34239884, 2021).
leprosy (5 papers, 2013 to 2022). Leprosy is a chronic infectious disease affecting primarily the skin and peripheral nervous system. "In previous studies, we demonstrated that FCN2 gene haplotypes associated with normal ficolin-2 levels have a protective effect against leprosy and that FCN1 gene -271DelT, -399A, -542G, -1981A polymorphisms were associated with susceptibility to leprosy." (PMID 28241035, 2017). "Furthermore, FCN2 and FCN1 haplotypes have protective effects against the susceptibility to leprosy per se." (PMID 28241035, 2017). "Another study investigating polymorphisms in the FCN1 gene showed a negative association of a haplotype with lepromatous leprosy compared to less severe forms of the disease." (PMID 35622698, 2022).
microscopic polyangiitis (5 papers, 2013 to 2023). Microscopic polyangiitis (MPA) is an inflammatory, necrotizing, systemic vasculitis that affects predominantly small vessels (i.e. small arteries, arterioles, capillaries, venules) in multiple organs. "For example, FCN1 was proven to be associated with monocytes in patients with microscopic polyangiitis." (PMID 31638917, 2019). "Elevated transcriptional levels of ficolin-1 in peripheral leukocytes and a heightened presence of ficolin-1-positive monocytes in glomeruli in individuals with microscopic polyangiitis have been documented." (PMID 37996869, 2023). "Upregulated mRNA levels of ficolin-1 in peripheral blood mononuclear cells, and a lot of ficolin-1–positive monocytes in the glomeruli in patients with microscopic polyangiitis have also been reported." (PMID 32915797, 2020). "Ficolin-1 mRNA level was also higher in PBMCs isolated from microscopic polyangiitis (MPA) patients than in PBMCs isolated from healthy volunteers." (PMID 24063402, 2013).
Sepsis (5 papers, 2015 to 2023). Sepsis is defined as life-threatening organ dysfunction caused by a dysregulated host response to infection. "Further, high serum ficolin-1 was associated with poor prognosis in patients with systemic inflammatory response syndrome due to sepsis." (PMID 32915797, 2020). "Notably, pDC B, characterized by high expression of S100A8, S100A9, FCN1 and CD14, was the dominant subtype in the ICU-Sepsis group." (PMID 37781404, 2023).
Stroke (5 papers, 2016 to 2021). Sudden impairment of blood flow to a part of the brain due to occlusion or rupture of an artery to the brain. "Reduced early (within 6 h of onset) ficolin-1, a marker of activation of the lectin pathway, is independently associated with unfavorable outcome in adult human stroke." (PMID 31417544, 2019). "The optimal cut-off value of ficolin-1 as a diagnostic marker of stroke was projected to be 0.25 μg/ml, which yielded a sensitivity of 87 % and a specificity of 84 %; at this cut-off, the odds ratio (OR) was 35.19 [95 % confidence intervals (CI 95 %) 13.63–90.86, p < 0.0001]." (PMID 26792363, 2016). "In conclusion, our study shows that the ficolins are consumed within 6 h after ischemic stroke and identifies for the first time ficolin-1 as a sensitive prognostic marker for stroke." (PMID 26792363, 2016). "In stroke patients, ficolin-1 (alias M-ficolin) serum levels are dramatically decreased at time point 6 h after the onset of symptoms, suggesting massive ficolin-1 consumption following cerebral ischemia." (PMID 27577570, 2016). "The time-course analysis showed that the increased ficolin-1 concentrations persisted at least up to 3–5 days after stroke (controls: 0.33 vs patients: 0.47 μg/ml, p < 0.01) with no changes in the other LP initiators." (PMID 26792363, 2016). "We now provide evidence of a specific role for ficolin-1 showing higher sensitivity compared to the other LP activators towards stroke outcome." (PMID 26792363, 2016). "Compared to controls, ficolin-1 levels are significantly lower when measured within 6 h after stroke and significantly higher when measured at longer time points, up to 3–5 days." (PMID 26792363, 2016). "The present multicenter observational study shows that LP in plasma is already consumed 6 h following stroke, consistent with LP activation, and that among the LP initiators evaluated in this study, ficolin-1 is selectively related to an unfavorable outcome 3 months after ischemic stroke." (PMID 26792363, 2016). "In patients suffering a stroke, plasma levels of C3a, C3, C4, C5, C5a, factor B, MBL, MASP-1/2, and MAC are all elevated and ficolin-1, ficolin-2, and ficolin-3 reduced." (PMID 31417544, 2019). "Plasma levels of the LP initiators ficolin-1, -2, and -3 and mannose-binding lectin (MBL) were measured in 80 stroke patients at 6 h only and in 85 patients at 48 h and later." (PMID 26792363, 2016). "For the prognosis of inflammatory response and stroke, ficolin-1 is also a strong prognostic, but it was not included in this retrospective study." (PMID 34063029, 2021). "The lack of association between ficolin-1 and the NIHSS, an index of neurological impairment, suggests that, besides the degree of initial injury, an overwhelming acute inflammatory host response significantly contributes to the pathogenesis of stroke and long-term outcome." (PMID 26792363, 2016).